ROS1 (ROS proto-oncogene 1, receptor tyrosine kinase)
Diseases named in the same sentence as ROS1 in open-access papers (continued):
Sharing a sentence is not in itself a finding about the gene and the disease.
tumor (continued). "In fact, the histological profile of tumours harbouring ROS1 or ALK translocation is very similar, featuring the presence of signet ring cells." (PMID 38793028, 2024). "ROS1 rearrangement have subsequently been identified in a variety of tumor types, including 1%-2% of NSCLCs." (PMID 38835380, 2024). "Next, in an effort to profile a ROS1+ specific expression signature, transcriptomes of ROS1+ tumor samples and ROS1+ patient-derived cell lines were compared to normal lung tissue or ALK/RET+ NSCLC specimens." (PMID 39737401, 2024). "Given that both ROS1+ NSCLC tumor specimens and ROS1+ patient-derived cell lines were used in this study, evaluating the key transcriptomic differences between tumor and cell line samples is particularly important." (PMID 39737401, 2024). "Chromosomal rearrangements resulting in ROS1 fusions drive tumor progression, and an appropriate diagnosis should be made on a clinical basis." (PMID 38629293, 2024). "It is possible to identify several ROS1 fusion partners as well as other oncogenic molecular targets, by using tumor DNA or RNA." (PMID 37511255, 2023). "We first determined the expression of cMet, ALK, and ROS1 in patient tumor tissue compared to tissue resection margin." (PMID 38144528, 2023). "Second, we found that ROS1 gene mutations, KRAS gene mutations, tumor stage, and the endocrine system diseases history are independent prognostic factors for PD-L1 positive patients." (PMID 37468609, 2023). "The Nomogram model intuitively reveals the important contributions of ROS1 gene mutations, KRAS gene mutations, tumor staging, and endocrine system disease history to prognosis prediction." (PMID 37468609, 2023). "Tumor growth is facilitated by ROS1 fusion protein–induced constitutive activation of ROS1 tyrosine kinase." (PMID 37917191, 2023). "ROS1D2033N induces the modification of ATP-binding pockets, resulting in the weakening of the ability of tumor cells to bind to ROS1-TKIs." (PMID 38187090, 2023). "Contrary to the wild-type ROS1, oncogenic fusion composed of the C’-terminal activation loop of ROS1 has already been discovered in various neoplasms, while there are several earlier reports in the case of GBM." (PMID 38201436, 2023). "For half of the biomarkers (AKT, ALK, BRAF, EGFR, Hedgehog, HER2, KRAS, MSI, NTRK, and ROS1), depending on the tumor type, the response rate ranged from 0 to 100%." (PMID 36639625, 2023). "Due to the presence of ROS1 tyrosine kinase domain, crizotinib, was used effectively against the tumor." (PMID 37958963, 2023). "A retrospective analysis of ROS1 positive solid malignancies identified by targeted RNA sequencing and whole transcriptome sequencing of clinical tumor samples performed at Caris Life Science (Phoenix, AZ)." (PMID 37853341, 2023). "ROS1/TRK/ALK-TKI repotrectinib, in the PDX model, showed tumor-suppressive effects on both treatment-naïve and solvent-front-mutant ROS1-rearranged NSCLC." (PMID 36911198, 2023). "We performed integrated molecular analyses of serial tumor and plasma samples, unveiling dynamic alterations in the ROS1 fusion driver and MET bypass axis at genomic and protein levels and the emergence of polyclonal resistance." (PMID 37923925, 2023). "We further verified this amplification with the tissue sample at time of progression on entrectinib and sotorasib by FISH which demonstrated a KRAS/CEP12 ratio of 11.5 and uniform ROS1 positivity across tumor cells." (PMID 36690705, 2023). "In this first large scale survey of ROS1 fusions identified by RNA NGS where only in-frame messenger RNA (mRNA) transcripts were reported, we identified 259 ROS1+ tumor samples by RNA NGS of tumor samples spanning 16 tumor types." (PMID 37853341, 2023). "Studies with CUTO64, derived at time of entrectinib progression, suggests the tumor remained partially dependent on ROS1 as maximal reduction in cell viability was achieved when ROS1 inhibition was paired with MAPK pathway inhibition." (PMID 36690705, 2023).
tumor (continued). "The model consists of ROS1 gene mutations, KRAS gene mutations, tumor staging, and endocrine system disease history, and has good predictive ability." (PMID 37468609, 2023). "Unexpectedly, the tumor shows TFCP2 rearrangement with coexistence of increased copy numbers of EWSR1 and ROS1 gene and MET gene mutation." (PMID 36998041, 2023). "Despite limitations, we were able to determine the characteristics of ROS1 fusions in a tumor agnostic manner." (PMID 37853341, 2023). "When NTRK or ROS1 undergoes fusion, their signaling pathways, MAPK or PI3K pathways, are constitutively activated, causing tumor hyperproliferation." (PMID 37372381, 2023). "In this study, we performed a large-scale pan-tumor survey of ROS1 fusions detected by next generation RNA sequencing to identify and characterize the molecular characteristics of ROS1+ solid tumors." (PMID 37853341, 2023). "Its limits are the need of an experienced pathologist due to the difficulty level to interpret the results, impossibility to know ROS1 fusion partners, and need of sufficient amount of tumor cells (more than 50)." (PMID 37511255, 2023). "Here, we identified four factors, including ROS1 gene mutations, KRAS gene mutations, tumor staging, and a history of endocrine system diseases, which are associated with treatment efficacy in patients with PD-L1 positive expression." (PMID 37468609, 2023). "mRNA expression of Met and ALK was significantly elevated in patient tissue and tumor cells isolated from primary tissue compared to their respective normal margins; however, ROS1 expression was barely detectable in both tumor samples and resected margins." (PMID 38144528, 2023). "Tyrosine kinase inhibitors (TKIs) target ROS1 and can block tumor growth and provide clinical benefits to patients." (PMID 38187090, 2023). "FISH ROS1 has been considered to be the “gold standard”, however we need more data from treatment studies to determine which test and algorithm identifies the clinically relevant ROS1 positive tumours." (PMID 37237384, 2023). "Standard assessment of tumor tissue includes rapid testing for EGFR mutations, ALK fusions and ROS1 fusions." (PMID 37948122, 2023). "In in vitro experiments, a combination of SHP2 inhibitors and ROS1-TKI increased the inhibition of tumor growth." (PMID 38187090, 2023). "Tumours harbouring mutations in genes such as EGFR and ERBB2, or gene rearrangements involving ALK, RET, or ROS1 are typically dependent on the oncogene for survival, with profound anti-tumour effects observed in response to the appropriate targeted therapy." (PMID 35326531, 2022). "It is also possible to detect potentially actionable activating genetic abnormalities specific to primary tumours (e.g., EGFR gene mutations or ALK and ROS1 gene rearrangements in patients with NSCLC)." (PMID 35884492, 2022). "In the case of secondary ROS-1 rearrangement, the patient’s tumor responded only to platinum–etoposide chemotherapy." (PMID 35200557, 2022). "It has been demonstrated that ROS-1 is a true oncogenic driver, and tyrosine kinase inhibitors (TKIs) targeting ROS-1 can block tumor growth and provide clinical benefit for the patient." (PMID 35200557, 2022). "Crizotinib treatment of ROS-1-positive NSCLCs controls the disease for a median duration of 19 months before the tumor develops crizotinib-resistance mechanisms and tumor progression is observed." (PMID 35200557, 2022). "Some tumors had molecular aberrations in frequently altered genes in NSCLC such as ALK, EGFR, KRAS or ROS1, as determined with the TruSight Tumor 170 sequencing panel in-house." (PMID 35329826, 2022). "A total of 45,438 solid tumor patients from the 3Dmed lab were evaluated, of which 92 patients were identified to have ROS1 rearrangements in the blood or tumor tissues." (PMID 36589752, 2022).
tumor (continued). "Ros1 transcripts for a proto-oncogene upregulated in many tumor cell lines were lower in NP over FAT cells, suggesting that increased proliferation in NP cells is not due to an aberrant phenotype." (PMID 36406265, 2022). "The ROS1 FISH+/IHC 3+ cases had significantly higher tumor grading and later stage than ROS1 IHC (-), including 0, 1+ and 2+ cases (all p < 0.0001)." (PMID 35628598, 2022). "A complementary FISH was performed confirming the presence of an ROS1 translocation in 80% of the tumour cells visualised." (PMID 36292136, 2022). "The mechanism of action is represented by the inhibition of the autophosphorylation of ALK gene and the molecular targets include IGF-1 R, InsR, and ROS1 and have an activity of 20 times higher against crizotinib–resistant tumor cell lines." (PMID 34082691, 2022). "At this time, it is not known if one of these newer agents would yield improved efficacy in these other tumor types with ALK or ROS1 fusions." (PMID 35233056, 2022). "Unfortunately, despite initial responses, ROS-1-positive NSCLCs develop resistances to crizotinib, allowing tumor progression, notably brain metastases." (PMID 35200557, 2022). "Five patients (26%), four with tumours harbouring CD74‐ROS1 fusions and one with a SLC34A2‐ROS1 fusion‐positive tumour showed emergence of acquired ROS1 resistance mutations (ROS1G2032R; ROS1F2004C/I) at PD, which were not present pre‐treatment." (PMID 35338679, 2022). "ROS1 gene fusion expression can drive cell proliferation and induce malignant transformation, which is common in many tumor cells, such as malignant gliomas." (PMID 36589752, 2022). "ROS-1 rearrangement appeared in one tumor as a resistance mechanism under EGFR-TKI and crizotinib was able to obtain a partial response." (PMID 35200557, 2022). "ROS1 translocation (hazard ratio (HR) = 11, p = 0.004), higher tumor grade (HR = 3.4, p = 0.003) and advanced clinical stage (HR = 3.3, p = 0.028) were poor prognostic factors in the univariate analysis." (PMID 35628598, 2022). "The targeted therapies are tailored to the patient based on the specific genetic background of the tumor (e.g., mutation or altered expression of EGFR, KRAS, BRAF, PIK3CA, PTEN, HER2, or gene fusion of ALK, ROS1, RET)." (PMID 35205667, 2022). "Neurotrophic receptor tyrosine kinase (NTRK) and ROS proto-oncogene 1 (ROS1) gene fusions are known oncogenic drivers across a range of tumour types, which result in constitutively active kinase activity." (PMID 33930659, 2021). "Others such as ROS1 rearrangement, RET fusion, HER2 mutation, NTRK1 fusion, and BRAF V600E mutation were detected in 7.9% of CSF and 11.1% of tumor tissues but only 4% in plasma." (PMID 34671549, 2021). "Next, we investigated the expression of CD82 and ROS1 mRNA by real-time qPCR in vector control and RelA/p65KD A549 and H1437 cancer cells grown as tumour xenografts in mice." (PMID 34503110, 2021). "In particular, 12 ROS1 patients were included and undergone tumor re-biopsy after radiological progression during treatment with a ROS1 inhibitor including crizotinib, ceritinib and brigatinib." (PMID 34884672, 2021). "Transcriptome analysis of vector control and Rel/p65KD A549 and H1437 cell tumours identified the proto-oncogene ROS1 and the LGR6 receptor gene amongst the downregulated genes, and the metastasis suppressor CD82 as one of the upregulated genes." (PMID 34503110, 2021). "Our review of the literature on IMT and other kinase fusions revealed, in addition to ALK rearrangements, the potential association of ROS1, NTRK, RET, or PDGFR beta alterations with the tumor." (PMID 34011083, 2021). "Of the 1117 patients included, 420 (38%) had KRAS mut tumours, 142 (13%) had EGFR mut tumours, 12 (1%) had ALK rearranged tumours, and 3 (0.3%) patients had ROS1 rearranged tumours." (PMID 34503114, 2021).
tumor (continued). "The presence of genetic alterations in tumor cells, such as EGFR and BRAF gene mutations, as well as ALK and ROS1 gene rearrangements, are indications for targeted therapies." (PMID 33921237, 2021). "Tumor genomic testing revealed that 28 patients (37%) carried an EGFR mutation, and three (4%) had an ALK/ROS1 rearrangement." (PMID 33794813, 2021). "At present, there are approved drugs for lung cancer, targeting tumor cells with mutated EGFR, ALK and ROS1 fusions, and mutated BRAF." (PMID 34217228, 2021). "No BRAF-positive patients were identified in this study, whereas 2.6% (1/43) of patients with stage III NSCLC were ROS1-positive; thus, crizotinib was used as per the guidelines as a first-line treatment for tumour recurrence." (PMID 34064047, 2021). "In our study, the prevalence of EGFR mutation in tumor cells was 45.55%, ALK rearrangement 8.11%, ROS-1 rearrangement 2.56%, which was similar to the results of other studies 23-25." (PMID 33859531, 2021). "Loss of RelA/p65 in human NSCLC cells grown as tumours in vivo lead to the upregulation of CD82/KAI1 and to the downregulation of ROS1 proto-oncogene mRNA levels." (PMID 34503110, 2021). "The prevalence of EGFR mutation in tumor cell was 45.55%, ALK rearrangement 8.11%, ROS-1 rearrangement 2.56%, PD-L1 expression positive 59.01%." (PMID 33859531, 2021). "Nevertheless, these data are a proof of concept of the potential efficacy of anti-ROS1 electrovaccination in hampering tumor growth and the metastatic spread of NSCLC." (PMID 32268572, 2020). "The ROS1 fusion group showed tumor shrinkage after treatment with crizotinib and anti-PD-L1 but not the G2032R group." (PMID 33324391, 2020). "Our study focused on the tumor microenvironment changes and its clinical potential for anti-PD-L1 therapy on ROS1 fusion NSCLCs." (PMID 33324391, 2020). "We first evaluated the radiologic features of the primary tumor in RET+ NSCLC compared to ALK+ or ROS1+ NSCLC." (PMID 32183422, 2020). "We also found clonal indels in NF2 in two tumors (cdRCC and mixRCC), and MET (mixRCC), SMARCB1 (pRCC1) and ROS1 (pRCC2) indels in one tumor each." (PMID 32555180, 2020). "Three samples were previously analyzed by orthologous kit and determined to be ALK fusion‐positive (n = 2) by IHC and ROS1 fusion‐positive (n = 1) by RT‐PCR using FFPE tumor tissues." (PMID 32351019, 2020). "Due to the EZR/ROS1 fusion, an in-label therapy with a CNS-penetrating ROS-inhibitor (ceritinib, crizotinib) was recommended by the molecular tumor board." (PMID 31903155, 2020). "Molecular analysis of tumor tissue revealed a ROS1:ARCN1 fusion, and therapy with a ROS1-inhibitor was therefore suggested but not feasible due to the unavailability of matching clinical studies in Europe at this time point." (PMID 33353026, 2020). "A 5′ deletion of ROS1 was detected by FISH in recovered CTCs from a patient with a known ROS1 rearrangement in the primary tumor (P 03)." (PMID 31947893, 2020). "Among 23 patients with ROS1-rearranged tumor, 20 patients who received at least one dose of crizotinib were included in the analyses of overall response." (PMID 33005033, 2020). "To test the potential of ROS1 immune-targeting to inhibit KL-ROS1 tumor growth, we electrovaccinated wt mice twice, at a 14-day interval, with plasmids coding for the extracellular and transmembrane sequence of either the m or hROS1 protein." (PMID 32268572, 2020). "In this latter case, we stratified patients who presented EGFR mutation or MET, ROS1 or ALK translocation, herein defined as mutated (Mut+), and compared them to the levels of tumor-associated caspase-4." (PMID 33187551, 2020). "ROS1, which belongs to one subfamily of kinase insulin receptor genes, is a proto‐oncogene, highly expressed in a variety of tumour cells." (PMID 31001929, 2019). "ROS1-rearranged lung tumors are “addicted” to ROS1 for growth and survival, leading to a pharmacological sensitivity of the tumor to ROS1-directed TKIs." (PMID 31323990, 2019).
tumor (continued). "We genotyped two tumor deposits from distinct anatomic sites in a patient with LUAD carrying both a U2AF1 S34F mutation and a ROS1 fusion." (PMID 31836708, 2019). "To explore different fusion genes in a single assay and to detect gene partners engaged in ALK (anaplastic lymphoma kinase) or ROS1 fusion, we evaluated two commercially available targeted RNA‐sequencing assays in a set of 37 tumor samples." (PMID 31651105, 2019). "A NGS assay showed that the tumor had a novel ROS1-ADGRG6 rearrangement generated by the fusion of exons of 1–33 of ROS1 on chr6: q22.1 to exons of 2–26 of ADGRG6 on chr6: q24.2." (PMID 31382924, 2019). "Tumours driven by either ALK or ROS1 involving fusion genes exhibit similar mechanisms of resistance to targeted agents." (PMID 31795465, 2019). "Within these alterations, important examples are ALK1 and ROS1 fusions, present in 3-5% and 1-2% of lung tumors, respectively, as well as in many other tumor types at lower prevalence rates." (PMID 31857850, 2019). "According to gene mutation types, tumor driver gene-derived inhibitors (including EGFR inhibitor, ROS1 inhibitor, and ALK inhibitor) have been screened and used for stratifying treatments in NSCLC patients." (PMID 31572680, 2019). "These CD74-ROS1 mutants expressing Ba/F3-bearing mice were treated with various doses of DS-6051b, and tumor growth and phospho-ROS1 were inhibited in the mice xenografts in a dose-dependent manner." (PMID 31399568, 2019). "Only three cases have ever been reported with concurrent ALK/ROS1 fusions in the same tumor indicating tumor heterogeneity." (PMID 31828041, 2019). "Unfortunately, the presence of a ROS1 fusion in this patient's tumor was identified only after she had experienced significant decline in her performance status and quality of life." (PMID 30719217, 2019). "Because it has a high homology with the kinase domain of ALK, ALK specific inhibitors, including crizotinib and ceritinib, revealed marked activity in ROS1-positive tumours." (PMID 31795465, 2019). "As a result, ROS1 rearrangement and PD-L1 positivity (tumor proportion score [TPS]: 100%) were detected." (PMID 30443294, 2018). "The patient’s tumor was tested for the alternative drivers ROS1 and MET that are known to be responsive to some ALK inhibitors but the results were negative." (PMID 28763012, 2017). "The ROS1 tyrosine kinase inhibitor (TKI) crizotinib has induced marked tumour shrinkage in ROS1-rearranged cancers." (PMID 28717217, 2017). "Four neoplasms were weakly immunostained for ROS1, and two neoplasms were weakly immunostained for L858R-specific EGFR." (PMID 26974543, 2016). "ROS1 was highly differentially expressed across tumor samples: mRNA levels were high (Cycle Threshold, Ct < 32) in 63% and low (Cycle Threshold, Ct > 32) in 38% of samples." (PMID 27329726, 2016). "As suggested by others, IHC testing of specimens containing at least 20 tumour cells and application of an H-score cut-off of >100 are highly concordant with ROS1 rearrangement by FISH or RT-PCR." (PMID 27535289, 2016). "We and another group reported the detection of ALK-rearrangement in CTCs ISET-enriched by filtration in NSCLC patients with an ALK-rearranged tumor as well ROS1-rearrangement in CTCs from NSCLC patients with an ROS1-rearranged tumor." (PMID 27417942, 2016). "It is clear however, that treating ALK and ROS1 mutant tumours with the appropriate targeted agents substantially improves patient’s outcome." (PMID 27350784, 2016). "Most ROS1-rearranged tumors were adenocarcinoma, and one case had focal squamous differentiation (accounting for 10%of the tumor volume)." (PMID 27648828, 2016). "Certainly, assuming drug treatment is available, response rates in treated patients whose tumours bear a ROS1 rearrangement are impressive." (PMID 27535289, 2016).